BCRP4 (BCR pseudogene 4)
Synonyms: BCR-4; BCR4; BCRL4
Gene: Unprocessed pseudogene on chromosome 22 (22,630,065 to 22,636,153, forward strand). Ensembl gene ENSG00000215456.
Diseases named in the same sentence as BCRP4 in open-access papers:
BCRP4 is named in the same sentence as 2 diseases in open-access papers, as found by Europe PMC text mining. Sharing a sentence is not in itself a finding about the gene and the disease.
BCRP4 shares sentences with these, for which no sentence is quoted: tumor (2 papers); infection (1).